INS (insulin)
Diseases named in the same sentence as INS in open-access papers (continued):
Sharing a sentence is not in itself a finding about the gene and the disease.
Hypoglycemia (continued). "Insulin treatment and GLP-1 receptor agonists work together, lead to steady glucose levels all day long, lower the risk of weight gain and hypoglycemia, and decrease the risk of long-term complications." (PMID 39273299, 2024). "In a cohort of 40 TPIAT recipients over 7 years from the Cleveland Clinic, 6 of 12 recipients developed symptomatic and severe hypoglycemia between 1 and 12 months following insulin independence." (PMID 39450137, 2024). "In conclusion, basal weekly long-acting insulin shows similar and better glycemic efficacy than daily basal insulin in T1DM and T2DM due to its association with less hypoglycemia, a reduction in the number of injections and its proven effectiveness." (PMID 38672255, 2024). "The results of oral glucose tolerance showed severe hypoglycemia, inhibition of insulin secretion, and decrease of C-peptide." (PMID 39435031, 2024). "Low-dose insulin demonstrated a significantly lower incidence of hypoglycemia and hypokalemia compared with the standard dose." (PMID 38827803, 2024). "It stimulates insulin secretion during euglycemia and hypoglycemia, and it stimulates glucagon secretion besides, glucose-dependent insulinotropic polypeptide increases tri-acyl glycerol (uptake in adipose tissue and decreases bone resorption." (PMID 39493778, 2024). "The MiTy trial reported a comparable incidence of neonatal hypoglycemia between insulin plus metformin versus insulin plus placebo in patients with T2DM (RR 0.82, 95% CI 0.52 to 1.30)." (PMID 37798604, 2024). "Both hypoglycemia during the initial intravenous insulin therapy phase (observed in 26.5% of patients) and hypoglycemia during the later subcutaneous insulin therapy phase (observed in 52.7% of patients) were associated with long-term mortality." (PMID 38594758, 2024). "The field of KATP channel pharmacology began in the 1940s with the serendipitous discovery that sulfonamide drugs used for treating typhoid fever also induced hypoglycemia due to stimulation of insulin secretion from the pancreas." (PMID 39303216, 2024). "Nighttime hypoglycemia following exercise is mainly due to depletion of glucose stores, impaired counter-regulatory hormone responses during sleep, and increased insulin sensitivity due to nighttime fasting." (PMID 38894740, 2024). "All of them had persistent/recurrent hypoglycemia after the first surgery even with pathology confirming the presence of a positive insulin neuroendocrine tumor." (PMID 38264280, 2024). "The overexpression of miR-155 results in hypoglycemia, improved glucose tolerance, and enhanced insulin sensitivity in peripheral tissues, with the imbalance of miRNAs impairing glucose and lipid metabolism." (PMID 38812051, 2024). "Compared to other hypoglycemic drugs, especially insulin, GLP-1RA produces more robust glucose-lowering effects, weight reduction, and lower risk of hypoglycemia." (PMID 38524632, 2024). "Substance P content of the adrenal medulla (as measured by RIA) also increased nearly seven-fold within 24 h in response to insulin-induced hypoglycaemia in rats." (PMID 38392992, 2024). "Subsequently, newer functionalities, including suspending insulin before hypoglycaemia occurs or providing small insulin boluses if there is an increasing glucose trend, have also been implemented." (PMID 39112642, 2024). "One study found that celiac-superior mesenteric ganglionectomy (CSMG) in rats significantly induced reduction in food intake and impaired the sympathoadrenal response to insulin-induced hypoglycemia." (PMID 39582948, 2024). "41% of the subjects treated with PERT and insulin and 42% of the control subjects treated with insulin had relevant hypoglycemia." (PMID 38331895, 2024). "Steady basal insulin analogs help prevent nighttime hypoglycemia, promoting safer overnight glucose management." (PMID 39734941, 2024).
Hypoglycemia (continued). "Recent advances in treatment, particularly hybrid closed-loop systems, have substantially improved quality of life and reduced the incidence of insulin-related acute complications such as severe hypoglycemia, hyperglycemia, and ketoacidosis." (PMID 39605938, 2024). "Studies summarized that the rate of severe hypoglycemia is 3.9% patient‐years among those with sulfonylureas, and those who administer insulin experience 2.5 severe hypoglycemia episodes per person yearly." (PMID 39431844, 2024). "In the current research, it was observed that after repeated episodes of insulin-induced severe hypoglycemia in rats, there was a significant decrease in the brain tissue level of catalase." (PMID 39004753, 2024). "Hypoglycemia is the most common adverse effect of insulin analogs detected in about 30% diabetic patients." (PMID 39457586, 2024). "By administering an intravenous bolus of insulin to induce severe hypoglycemia, the ITT stimulates a counter-regulatory response that evaluates the entire HPA axis (sensitivity was recently reported to reach 100%, with specificity at 87%)." (PMID 39459358, 2024). "Male global Alms1 KO mice showed reduced insulin-induced hypoglycemia, while MSC KO in males produced a trend towards reduction." (PMID 38583571, 2024). "Studies have shown that 58%–64% of patients receiving insulin and non-insulin treatments require medical assistance to treat hypoglycemia over a period of 6–12 months." (PMID 39123214, 2024). "A previous study investigated that basal insulin had more advantages than premixed insulin in reducing GV and hypoglycemia." (PMID 39075573, 2024). "Considering only the cost of insulin, the use of IGlar for patients with T2D and severe hypoglycemia resulted in a yearly average NBI of 174.9 million Thai baht (THB) (5.1 million USD)." (PMID 39877917, 2024). "Patients with more severe T1D require more time for glucose levels to normalize after insulin-induced hypoglycemia and experience prolonged low plasma glucagon levels, highlighting the role of glucagon in managing hypoglycemia." (PMID 39594662, 2024). "These barriers include delays in initiating or adjusting Insulin, needle phobia leading to missed daily injections, instances of missed Insulin doses, Insulin discontinuation, and the occurrence of hypoglycemia." (PMID 38566252, 2024). "The rate of minor hypoglycemia has been shown to increase as high as 42% with concomitant sulfonylurea and/or insulin therapy." (PMID 38861153, 2024). "Fear of hypoglycemia often leads to excessive avoidance behaviors such as excessive food intake and self-reduction of insulin dose, which worsen glycemic control, thus leading to complications or aggravating their development." (PMID 38872219, 2024). "Overall, these results together with the in vivo experiments delineate a hitherto unrecognized signaling pathway for the observed rise in plasma adrenaline in response to insulin-induced hypoglycemia." (PMID 39375537, 2024). "Given the glycemic fluctuations induced by glucagon and the subsequent rebound insulin, diligent glucose level monitoring throughout the test is imperative to detect any early hyperglycemia or late hypoglycemia." (PMID 38461479, 2024). "This was later confirmed at Auguste Loubatieres by showing that sulfonylurea drugs stimulated insulin secretion and hypoglycemia in dogs." (PMID 38302135, 2024). "Following the introduction of the new guidelines, not only was there a reduced usage of insulin/dextrose but in those who did receive insulin/dextrose, there was a 73% reduction in the incidence of hypoglycaemia (P = 0.04)." (PMID 38871123, 2024). "This physiological state, with its antagonistic effects on insulin actions, serves to prevent hypoglycaemia while also disrupting energy balance by redirecting energy fluxes from muscles towards abdominal fat depots." (PMID 39194497, 2024).
Hypoglycemia (continued). "Histaminergic neurons from distinct subpopulations display specific responsiveness to different stimuli such as restraint, insulin-induced hypoglycemia, or foot shock." (PMID 38288837, 2024). "Performed sensitivity analyses indicate that the publication date did not significantly impact meta-analysis results for primary outcomes, including unexplained hypoglycemia, HbA1c, and the total daily insulin dose." (PMID 38215209, 2024). "Moderate hypoglycemia days comprised 31 insulin-days (3.1%) involving hospital pumps compared with 35 (4.5%) involving home pumps and 830 (5.1%) involving injections (P = .02)." (PMID 38324312, 2024). "In conclusion, we report the benefit of daily subcutaneous liraglutide to treat spontaneous severe hypoglycemia despite insulin independence following TPIAT." (PMID 39450137, 2024). "Fear of hypoglycemia and its potential consequences for patients, including cognitivedysfunction, can add to the stress of an insulin regimen." (PMID 38224978, 2024). "In particular, in the overall population, 107 participants experienced an episode of severe hypoglycaemia, with 30 of the cases occurring in a single trial arm wherein participants were randomised to prandial insulin." (PMID 38613667, 2024). "The precise window following insulin/dextrose in which hypoglycaemia occurs remains debated; as a result, blood glucose monitoring varies across institutions." (PMID 38871123, 2024). "Systems that deliver glucagon in addition to insulin can be more effective during, and in preventing hypoglycemia episodes than insulin delivery alone." (PMID 39390689, 2024). "Among the subjects, 44 patients received oral hypoglycemia drugs, 83 were administered insulin treatment, and 26 patients were prescribed a combination of both treatments." (PMID 39020001, 2024). "During hypoglycaemia, inappropriate levels of insulin and C-peptide result in the inhibition of lipolysis, gluconeogenesis and ketogenesis, leading to a reduction of the brain’s alternative energy sources." (PMID 38952388, 2024). "Structured education on insulin administration, hypoglycemia training, blood glucose targets, and exercise management have also been shown to improve awareness of hypoglycemia." (PMID 38894740, 2024). "They only check blood glucose during scheduled visits to healthcare facilities, whereas self-monitoring of blood glucose in DM patients, especially insulin users, is essential to prevent severe hypoglycemia." (PMID 38243951, 2024). "Following birth, a shift to intermittent feeding and elevated plasma glucose requires an increase in β-cell insulin secretion for efficient nutrient absorption, as well as a suppression of insulin release during fasting to avoid hypoglycemia." (PMID 38700926, 2024). "Acute hypoglycemia is the most feared adverse event in people treated with insulin or sulfonylureas." (PMID 39568409, 2024). "Compared to placebo, GLP-1 RAs can significantly reduce body weight and basic insulin dosage, while DPP-4i and SGLT-2i have a lower risk of hypoglycemia." (PMID 39072050, 2024). "The effects of structured education for intensive insulin treatment in reducing mean HbA1c values and improving hypoglycemia or QOL are already well known." (PMID 39259960, 2024). "A large number of studies have recently used insulin to induce single and recurrent hypoglycaemia as it is a more physiologically relevant stimulus to mimic the human HAAF phenomenon." (PMID 38392992, 2024). "Hyperkalemia treatment with insulin commonly results in hypoglycemia, which is also a common complication among patients with reduced kidney function." (PMID 39274318, 2024). "The combination of neuroglycopenic symptoms relieved by carbohydrate and documented hypoglycemia fulfilled Whipple's triad, prompting evaluation for an insulin-secreting tumor." (PMID 39677258, 2024).
Hypoglycemia (continued). "Since MIN6 cells are insulin-secreting tumor cells that proliferate and secrete insulin autonomously in vivo, all of our nude mouse recipients experienced hypoglycemia within 2 weeks after implantation of MIN6 cells embedded in Matrigel." (PMID 38920672, 2024). "Insulin therapy increased the odds of severe hypoglycaemia by threefold (aOR: 3.39, n=0.005), compared to those without insulin therapy." (PMID 38387535, 2024). "A previous study reported that isomaltulose is less likely to elevate blood glucose levels, is insulin-hypoallergenic, inhibits the elevation in blood glucose level from other carbohydrates, and avoids hypoglycemia through blood glucose stabilization." (PMID 39683513, 2024). "Studies on murine SOD1G93A ALS models revealed elevated glucagon levels following fasting or insulin-induced hypoglycemia despite minimal changes in overall blood glucose levels." (PMID 38791099, 2024). "In general, insulin Gla-300 was well tolerated, and a serious drug-related event occurred in 2.4% of the population, usually in the form of hypoglycemia." (PMID 38982528, 2024). "Inappropriate insulin response leads to hyperinsulinemic hypoglycemia (HH), characterized by detectable insulin levels with hypoglycemia, hypoketonemia, and hypofattyacidemia." (PMID 39421536, 2024). "Insulinoma is a common neuroendocrine tumor that can secrete endogenous insulin, resulting in episodes of recurrent hypoglycemia." (PMID 39156287, 2024). "An analysis of insulin-related emergency department visits identified patient self-management as the most common precipitant to insulin-related hypoglycemia and errors—patients incorrectly managed their food intake and insulin products at home." (PMID 38684080, 2024). "Endogenous hyperinsulinemic hypoglycemia is a condition characterized by dysregulated insulin secretion and/or clearance, leading to recurrent episodes of hypoglycemia." (PMID 39659391, 2024). "Hemodialysis was administered to eliminate potassium from the body due to the ongoing hypoglycemia, which restricted the utilization of insulin to facilitate the movement of potassium into cells." (PMID 39347364, 2024). "One of the major indications for using CGM is unexpected hypoglycemia in patients on multiple injections of insulin per day, hypoglycemia unawareness, or labile DM." (PMID 39149659, 2024). "Our patient presented with symptomatic fasting hypoglycaemia, and on evaluation, she was found to have high levels of fasting insulin and C-peptide levels." (PMID 38428138, 2024). "Hypoglycemia is one of the main adverse reactions to insulin, and severe hypoglycemia is life-threatening." (PMID 38803476, 2024). "Acromegaly is a rare disorder characterized by excessive production of growth hormone (GH) from a pituitary tumor, typically leading to elevated glucose levels due to increased insulin resistance; hypoglycemia is rare." (PMID 38765413, 2024). "Octreotide directly inhibits insulin release from the pancreas, thus preventing rebound hypoglycemia." (PMID 39347364, 2024). "Fasting insulin level was high (190 mIU/L, reference values (RV): 5–25) on Architect i2000 (an assay recognizing insulin analogs) despite normal blood C-peptide (4.5 μg/L, RV: 0.8–5.2) and slight hypoglycemia (4.5 mmol/L, RV: 4.6–6.1)." (PMID 39071705, 2024). "For seniors over 60 years, severe insulin-related hypoglycemia and other ADRs often result in emergency consultations, hospitalizations, and an increased risk of mortality." (PMID 39457586, 2024). "These defects cause neonatal hyperinsulinisms, characterized by unregulated insulin secretion from β-cells, leading to severe hypoglycemia." (PMID 38980630, 2024). "During the admission, she was noted to have frequent episodes of hypoglycemia despite conservative insulin dosing and high urine output with glucosuria, which seemed out of proportion to her glucose levels and fluid status." (PMID 38744309, 2024).
Hypoglycemia (continued). "Insulinomas are rare pancreatic neuroendocrine tumors (NETs) characterized by autonomous insulin secretion leading to hypoglycemia." (PMID 39677258, 2024). "Our results demonstrated that 44 patients received oral hypoglycemia drugs, 83 were administered insulin treatment, and 26 were prescribed a combination of both treatments." (PMID 39020001, 2024). "Level 1 hypoglycemia (glucose <70 mg/dL) was identified more often in the Early glargine group during IV insulin infusion, but this trend reversed for both level 1 and level 2 hypoglycemia in the 12 h following IV insulin discontinuation." (PMID 39136541, 2024). "The baseline data demonstrate that there is a considerable incidence of iatrogenic hypoglycaemia that arises from the use of insulin/dextrose for the management of hyperkalaemia in patients with renal disease." (PMID 38871123, 2024). "The diagnosis of HI is made on the basis of increased insulin action and/or inadequate suppression of plasma insulin during either spontaneous or fasting-induced hypoglycemia." (PMID 37454648, 2024). "Subsequently, the patient experienced a significant decrease in insulin requirements, ultimately leading to the suspension of insulin therapy due to persistent hypoglycemia." (PMID 39130944, 2024). "Venous blood was drawn for glycaemia, insulin and C-peptide at admission and at established intervals, in case of symptoms of hypoglycaemia or if CBG ≤ 45 mg/dl, when the fast would be suspended." (PMID 38451386, 2024). "Insulinomas are rare neuroendocrine tumors that predominantly occur in the pancreas and secrete insulin, leading to hypoglycemia." (PMID 39100462, 2024). "Insulinomas are typically benign pancreatic neuroendocrine tumors that secrete insulin inappropriately, leading to episodes of hypoglycemia." (PMID 39125476, 2024). "In our study, 81.8% of the cases admitted to the emergency department with hypoglycemia were detected to be on sulfonylurea or insulin treatment." (PMID 39364503, 2024). "Two independent in vivo experiments were conducted to evaluate the effectiveness of P2-GCGin reversing or preventing insulin-induced deep hypoglycemia." (PMID 39634211, 2024). "Insulin-induced hypoglycemia accelerates gastric emptying substantially, even in individuals with gastroparesis and autonomic neuropathy." (PMID 39568409, 2024). "GLP-1-based therapy also slows gastric emptying, which has benefits (lowering postprandial glucose), but also potential risks (eg, hypoglycemia in individuals on insulin or sulphonylurea therapy)." (PMID 39568409, 2024). "Despite such a low glycemic control rate, level-2 hypoglycemia (<54 mg/dL) occurs quite frequently, ranging from once every 6 days to once every 2 days, in patients receiving multiple daily insulin injection treatment." (PMID 39259960, 2024). "Next, the in vivo efficacy ofthe GCG-micelleto prevent deep hypoglycemia was assessed by injecting insulin andthe micelles simultaneously (combined preparation) at time 0 of theexperiment." (PMID 39634211, 2024). "For instance, glucagon release is stimulated by hypoglycemia, starvation, exercise, and protein-rich meals, and insulin release is stimulated by a hyperglycemic condition." (PMID 38921471, 2024). "Somatostatin inhibits insulin release, and thus its analogue sandostatin can prevent hyperinsulinemia induced hypoglycemia in P. falciparum malaria." (PMID 39492784, 2024). "Insulin’s additive effect makes it challenging to determine the extent the GLP-1 RA contributed to the hypoglycemia." (PMID 38861153, 2024). "Our research aimed to critically evaluate and explain the potential relationship between lipohypertrophy and outcomes related to glycemic control (e.g., hypoglycemia events, HbA1c, and glycemic variability) and insulin dosing." (PMID 38215209, 2024).